KRAS (KRas proto-oncogene, GTPase)
Diseases named in the same sentence as KRAS in open-access papers (continued):
Sharing a sentence is not in itself a finding about the gene and the disease.
colorectal cancer (continued). "In summary, this study is the first to analyze the role of molecular cooperation of HIPK2 with KRAS signaling, already associated to colorectal cancer, in the KRAS-driven tumorigenesis of the pancreas using mice with tissue-specific expression of oncogenic KRAS and Hipk2-KO." (PMID 39342278, 2024). "KRAS is one of the most frequently mutated oncogenes in cancer: Approximately 30 to 40% of patients with colorectal cancer harbor missense mutations in KRAS, and KRAS mutations have long been associated with increased tumor aggressiveness, resistance to treatment, and poor patient outcomes." (PMID 39018396, 2024). "In contrast, KRAS mutations in colorectal cancer typically require APC loss to drive frank adenocarcinoma, suggesting that RAS oncogenic signaling may act as a cooperative oncogenic driver in this case." (PMID 38593348, 2024). "Interestingly, REG4 expression was recently shown to be induced by KRAS mutation in colorectal cancer cells, and act as a driver of K-RAS-induced tumorigenic effects." (PMID 38066386, 2024). "Furthermore, utilising KRAS-driven colorectal cancer models we show that loss of wild-type KRAS promotes sensitivity to MEK inhibition in vivo." (PMID 38168062, 2024). "As KRAS gene mutations located at positions Gly12 and Gly13 are particularly associated to the progression of oncogenesis, we screened the occurrence of these two mutations in tumors and healthy tissues of 135 patients with a colorectal cancer." (PMID 39722416, 2024). "Additionally, we observed a significant (p = 0.03) association between KRAS status and colorectal cancer." (PMID 39673361, 2024). "In addition, investigation of KRAS mutations in gastric and colorectal cancer revealed a p value of 0.38." (PMID 39673361, 2024). "For instance, non-small-cell lung cancer requires the presence of EGFR, ALK, ROS1, BRAF, MET, RET, and KRAS genes, while the prognosis of colorectal cancer patients can be determined by the mutation of KRAS, NRAS, BRAF, and HER2 genes, as well as microsatellite instability analysis." (PMID 39194571, 2024). "Thus, APC alterations were highly associated with colorectal cancer; KRAS alterations and normal APC were highly associated with pancreatic cancer; and CDKN2A alterations and normal APC and KRAS were highly associated with biliary tract cancer." (PMID 38672586, 2024). "Colorectal cancer patients with KRAS mutations are often associated with poor prognosis, less responsive to certain targeted therapies, and have a higher risk of disease recurrence when compared to patients with wild-type KRAS." (PMID 39273409, 2024). "The purpose of this study was to test the hypothesis that certain clinical and tumor characteristics of KRAS c.34G>T (p.G12C)‐mutated colorectal carcinomas might differ from those of other KRAS‐mutated tumors and KRAS‐wild‐type tumors." (PMID 39039804, 2024). "Therefore, it is of particular interest to comprehensively understand the features of KRAS c.34G>T (p.G12C)‐mutated colorectal carcinomas." (PMID 39039804, 2024). "However, unique features of KRAS c.34G>T‐mutated colorectal carcinoma (compared with KRAS‐wild‐type and other KRAS‐mutated tumors) need to be further elucidated." (PMID 39039804, 2024). "Hence, our study has provided new intriguing findings on colorectal carcinomas with the specific KRAS c.34G>T (p.G12C) mutation." (PMID 39039804, 2024). "We hypothesized that KRAS c.34G>T (p.G12C)‐mutated colorectal carcinoma might be a distinct tumor subtype." (PMID 39039804, 2024). "Then, the transcripts were analyzed so that their function with respect to KRAS-mutated colorectal cancer could be identified." (PMID 37873786, 2023). "Regarding KRAS mutations, our results suggest that Fn may specifically infect colorectal cancer with KRAS mutations at low levels compared with colorectal cancer with non-KRAS mutations." (PMID 37772997, 2023).
colorectal cancer (continued). "The difference in carrier rates of EGFR mutations between early‐onset and late‐onset lung cancer cohorts is highly debatable according to a previous study, though the lower KRAS mutation carrier rate in early‐onset colorectal cancer is consistent with one previous report." (PMID 37610374, 2023). "Furthermore, miR-99b, KRAS mutations, and Akt are risk factors for the overall survival of colorectal cancer." (PMID 37639911, 2023). "The first is that the Wnt pathway signal is involved in the regulation of CERS4 or the Wnt pathway may be involved in the KRAS mutation in colorectal cancer." (PMID 37758931, 2023). "Low levels of Fn may specifically infect colorectal cancer with KRAS mutations as compared with colorectal cancer with non-KRAS mutations and this association can be detected in either FF or FFPE colorectal cancer samples." (PMID 37772997, 2023). "Moreover, the addition of simvastatin to mFOLFOX6 + cetuximab was shown to increase the efficacy of FOLFOX6 + cetuximab, reduce the incidence of side effects, including peripheral neuropathy, and prolong OS of KRAS-mutated colorectal cancer patients." (PMID 37069612, 2023). "Moreover, Kirsten rat sarcoma viral oncogene homolog (KRAS) mutation is one of the most common gene mutations and is a frequent driver in lung cancer, colorectal cancer, and pancreatic cancer (PC)." (PMID 36761724, 2023). "Given the putative regulation of CLDN4 by AP-1 through AP-1-binding sites in its promoter, mRNA expressions of CLDN4 within molecular subsets of colorectal cancers were examined taking into consideration the presence of mutations in the upstream regulators KRAS and BRAF." (PMID 37998722, 2023). "Additionally, simvastatin resensitized patients with cetuximab-resistant KRAS-mutated colorectal cancer to cetuximab, and taking a statin after colorectal cancer diagnosis reduced the risk of death from colorectal cancer." (PMID 37069612, 2023). "Indeed, the response rate to KRAS p.G12C mutations in colorectal cancer, a disease that has been extensively studied, exhibits considerable variability and does not exceed 7%." (PMID 37759584, 2023). "KRAS mutation has a significant influence on the progression and treatment of colorectal cancer." (PMID 37869102, 2023). "Indeed, treatment of KRAS-mutated colorectal cancer cells with SJ-C1044, a type IIa RAF inhibitor, resulted in the inhibition of MEK and ERK activity in a concentration-dependent manner, without any evidence of paradoxical activation." (PMID 37504287, 2023). "In colorectal cancer, cells with the KRAS mutation are highly dependent on RAD51 for survival." (PMID 36262061, 2023). "Activating mutations in the KRAS gene are present in more than 80% of pancreatic cancers and more than 30% of colorectal cancers and have been shown to be significantly associated with the poor prognosis of many cancers, such as pancreatic cancer and non-small cell lung cancer." (PMID 37360159, 2023). "KRAS mutations are frequently found in colorectal cancer patients and could be a predictive marker for metastatic disease." (PMID 37373047, 2023). "Because TNO155 has been shown to effectively reduce drug-induced feedback activation in KRAS-G12C–mutated lung and colorectal cancer cells, we tested combination drug treatments on LAN-6 neuroblastoma xenografts, which harbor both ALK-D1091N and KRAS-G12C mutations." (PMID 38032104, 2023). "For this reason, in addition to HEK293 cells, we performed a proteomic screen in HKe-3 cells, a colorectal cancer cell line derived from HCT116 cells where the oncogenic KRASG13D allele was knocked out that tolerates overexpression of KRAS mutants and we used before to perform proteomics screens." (PMID 37627169, 2023). "In addition, KRAS mutations are common in more than 80% of pancreatic cancer cases and more than 30% of colorectal cancer cases." (PMID 37705174, 2023).
colorectal cancer (continued). "KRAS mutations detected in the ctDNA of colorectal cancer patients sampled at the time of tumor resection might predict a poor response to first-line chemotherapy." (PMID 37511664, 2023). "This study aims to establish whether a valid association between VTE risk and KRAS-activating mutations in colorectal cancer exists, a step necessary towards the development of more up-to-date thromboprophylaxis protocols." (PMID 38069251, 2023). "It has been reported that colorectal cancer patients with a mutation allele frequency (MAF)/variant allele frequency (VAF) of 0.1~5% in KRAS mutation in tumor tissue might benefit from the addition of anti-EGFR (cetuximab) to FOLFIRI chemotherapy." (PMID 37511664, 2023). "More than a third of all colorectal cancers have a KRAS mutation." (PMID 37190303, 2023). "We hypothesized that different KRAS/BRAF mutational statuses of colorectal cancer cell lines affect the effectiveness of HAMLET anticancer and mitochondrial activity." (PMID 37099199, 2023). "Additionally, applying these inhibitors is limited to a small number of tumors with KRAS mutation, i.e., in 13 % of KRAS mutated NSCLCs, in 1 to 3 % of KRAS mutated colorectal cancers and in 1 to 2 % of KRAS mutated pancreatic cancers." (PMID 36313934, 2023). "While HES1 expression is normal in benign hyperplastic polyps and normal colon tissue, HES1 expression is often lost in sessile serrated adenomas/polyps (SSAs/SSPs) and colorectal cancers (CRCs) such as those right-sided CRCs that commonly harbor BRAF or KRAS mutations." (PMID 36824959, 2023). "KRAS mutations as biomarkers predict resistance to drugs such as cetuximab in colorectal cancer." (PMID 37513471, 2023). "Analyzing patients with colorectal cancer in the Republic of Tatarstan (Russian Federation), we found that the total mutation rate of KRAS was about 57% and the frequency of mutant KRAS occurrence in patients aged over 60 years decreased sharply, compared with younger ones, and did not exceed 10%." (PMID 36674440, 2023). "KRAS mutations are strongly implicated in lung, pancreatic, and colorectal cancers." (PMID 37662925, 2023). "The mutated KRAS can drive the invasion and maintenance of metastasis of colorectal cancer, and it may also be a potential biomarker and therapeutic target for metastatic colorectal cancer." (PMID 37546388, 2023). "Although genetic alterations and tumorigenesis processes remain unclear, mucinous differentiation of colorectal cancers are associated with high frequency of mutations in KRAS or BRAF." (PMID 37496011, 2023). "A substantial proportion of colorectal cancers harbor non-G12C KRAS mutations." (PMID 37190303, 2023). "For example, we recently used a mathematical model to identify the mechanism that explains why colorectal cancer patients with a KRAS G13D mutation benefit from treatment with EGFR inhibitors despite KRAS mutations more commonly causing resistance to EGFR inhibitors." (PMID 37823369, 2023). "Furthermore, the KRAS G12C variant is less frequent in colorectal cancers, in which other variants are more represented, such as G12V, G12E, and G12A, which currently have no target treatments available." (PMID 36836752, 2023). "TMEM211 shows different expression levels between KRAS G12 mutated and wild-type colorectal cancer." (PMID 37367036, 2023). "KRAS mutation is found in approximately 35–45% of colorectal cancers." (PMID 37370699, 2023). "In colorectal cancer, KRAS mutation is also widely associated with poor prognosis." (PMID 37108755, 2023). "Therefore, although KRAS mutation is relatively common (detected in 30–40% of colorectal cancers), its mechanism in tumour development and invasion in rectal cancer is still unclear." (PMID 38087207, 2023).
colorectal cancer (continued). "In conclusion, triphasic enhanced CT radiomics models were constructed to predict KRAS mutation status in colorectal cancer, and the results showed that the AP, VP, and DP models could better predict KRAS mutation status in the training and validation cohorts." (PMID 37311935, 2023). "In this study, we used computed tomography (CT)-based radiomics signatures to predict the mutation status of KRAS in patients with colorectal cancer (CRC) and to identify the phase of radiomics signature with the most robust and high performance from triphasic enhanced CT." (PMID 37311935, 2023). "In terms of the prognostic value of KRAS mutation in colorectal cancer, the results from previous studies are also heterogeneous, suggesting that different mutation variants of KRAS confer distinct prognoses on the overall survival of colorectal cancer patients." (PMID 37511664, 2023). "KRAS gene is highly mutated in up to 50% of colorectal cancer." (PMID 37869102, 2023). "KRAS mutation is the most frequent oncogenic aberration in colorectal cancer (CRC)." (PMID 35836817, 2022). "However, the upregulation of hsa-miR-127-3p in the colorectal cancer tissue was associated with KRAS mutation." (PMID 35559021, 2022). "Taken together, these results suggest that where KRAS mutation is a biomarker of cetuximab response in colorectal cancer, in HNSCC, KRAS amplification may be a predictive marker of cetuximab resistance." (PMID 35011716, 2022). "KRAS mutation is one of the dominant gene mutations in colorectal cancer (CRC)." (PMID 35305671, 2022). "In turn, Cu metabolism may be a promising target for colorectal cancers harboring KRAS mutations (Aubert, Nandagopal & Roux, 2020)." (PMID 35433131, 2022). "The reasons for the different results of these two studies may be the types of colorectal cancers studied are different, one is KRAS mutated, and the other is common undetected mutations." (PMID 35874764, 2022). "A similar induction of mitochondrial vulnerability has been previously observed when introducing KRAS mutations into colorectal cancer cell lines of both Wnt‐low and Wnt‐high groups, indicating that Wnt signaling is not the only pathway important for directing metabolic rewiring in cancer." (PMID 35904277, 2022). "A mutated KRAS, hence, is negatively associated with an amplification of KRAS in colorectal cancer." (PMID 36291770, 2022). "As we all-known that KRAS mutations were one of the most prominent oncogenes in colorectal cancer." (PMID 35910359, 2022). "For example, KRAS is either mutated or amplified in colorectal cancer." (PMID 36291770, 2022). "KRAS mutation is responsible for 40–50% of colorectal cancers (CRCs)." (PMID 35562390, 2022). "KRAS mutations are one of the most common gene mutations linked to cancer, presenting in approximately 25% of all tumors, especially pancreatic, lung, and colorectal cancers." (PMID 35154489, 2022). "In addition, when conducting a KRAS mutation test in patients with colorectal cancer that contains an adenoma component, only the invasive carcinoma component should be harvested to ensure accurate test results." (PMID 36083889, 2022). "Additionally, we found that the other EGFR-positive KRAS mutations colorectal cancer, SW620(G12V), and HCT116(G13D), cell viability was affected by R9VH36 treatment." (PMID 35578244, 2022). "Furthermore, it has also been demonstrated in colorectal cancer cell lines that KRAS G13D mutation can mediate radioresistance through the transcriptional upregulation of NRF2, followed by its nuclear translocation and the concomitant overexpression of 53BP1." (PMID 35359456, 2022). "Mutations of the KRAS gene are found in about 50% of colorectal cancer cases." (PMID 35682714, 2022). "KRAS gene mutations occurred in approximately 35-45% of colorectal cancer patients." (PMID 35685832, 2022).
colorectal cancer (continued). "Prediction of KRAS/NRAS/BRAF mutations in colorectal cancer (CRC)." (PMID 35740526, 2022). "In blood samples from five patients with colorectal cancer, this method could accurately detect the single-strand KRAS G12DM mutation." (PMID 36551512, 2022). "In addition, in colorectal cancer with KRAS or BRAF mutations, lung cancer with KRAS mutations, and pancreatic cancer, GLUT1 expression is increased because of an accelerated glycolytic pathway, resulting in higher DHA absorption." (PMID 36203466, 2022). "The investigation found that when this combination drug therapy was applied to two colorectal cancer cells carrying both β-catenin and the KRAS mutation, the Ls174T cells showed inhibition of MAPK signaling while the DLD-1 cells inhibited FOS expression, which downregulates RalA." (PMID 35409064, 2022). "Studies have demonstrated that OVs can inhibit the growth and distant metastasis of colorectal cancer cells by lysing CRC cells, inducing apoptosis, and reversing TME, and have shown exciting results in treating CRC peritoneal metastases and KRAS-mutated colorectal cancer." (PMID 35911673, 2022). "Of note, it has been reported that ERK5 is dispensable for proliferation of colorectal cancer cells carrying KRAS/BRAF mutations, suggesting that genetic mutational background must be considered to establish the exact role of ERK5 in proliferation of different cancer types." (PMID 36123565, 2022). "KRAS mutation accounts for 30–50% of human colorectal cancer (CRC) cases." (PMID 35183163, 2022). "KRAS G12C is the most frequent mutation in pancreatic and colorectal cancer." (PMID 36104708, 2022). "Studies have found that mutations in KRAS were found in 30%–50% of colorectal cancers." (PMID 35910359, 2022). "Adding to the emerging understanding between specific alterations and histology, KRAS G12D is the most common variant observed in colorectal cancer and is also the most common variant observed in KRAS mutant adenocarcinoma with enteric differentiation where IHC profiles can be indistinguishable." (PMID 36136862, 2022). "Another study has shown global down-regulation of circRNAs in DLD-1 and DKO-1 colorectal cancer cells (containing KRAS mutant allele) compared to DKs-8 cells (containing only wild type alleles of KRAS), representing an extensive influence of mutant KRAS on expression profile of circRNAs." (PMID 35139853, 2022). "Oncogene KRAS mutations are rather rare in BRAF mutant colorectal cancers, occurring in 10% of such cancers in TCGA and in about 5% in the DFCI cohort, compared with 37.8% and 31.6% in cancers with BRAF and PIK3CA wild type and 64.8% and 43.3% of cancers with BRAF wild type and PIK3CA mutations." (PMID 36079062, 2022). "We clinically validated the limit of blank (LOB) and the limit of quantification (LOQ) of assays for the clinically most relevant somatic variants BRAF p.V600E and KRAS p.G12/p.G13 in colorectal cancer (CRC) in a study cohort encompassing a total of 212 plasma samples." (PMID 35159118, 2022). "Finally, both cell lines and a murine xenograft model of colorectal cancer with KRAS mutation demonstrated that high concentrations of ascorbate enhanced the cytotoxic effect of chemotherapy." (PMID 35744943, 2022). "In addition, KRAS gene mutation indicates poor response of colorectal cancer patients to anti-EGFR targeted therapy." (PMID 36544770, 2022). "In addition, KRAS mutations were more frequently identified in colorectal cancers that contained an adenoma component." (PMID 36083889, 2022).